CD27 (CD27 molecule)
Diseases named in the same sentence as CD27 in open-access papers (continued):
Sharing a sentence is not in itself a finding about the gene and the disease.
intestinal tumor (1 paper, 2025). "Among these, CD27 was highly expressed in the intestinal tumor stroma, lymphoid follicles, and T-cell membranes of normal intestinal mucosa and was positively correlated with patient survival." (PMID 40690457, 2025).
kidney cancer (1 paper, 2021). Primary or metastatic malignant neoplasm involving the kidney. "Therapies targeting the CD27/CD70 axis have furthermore been shown to have some, though not dramatic, clinical effects in kidney cancer patients." (PMID 33996677, 2021).
kidney damage (1 paper, 2022). "More recently, the effects of the immunosuppressive treatment over a IgD- CD27- B cell subpopulation (double negative; DN) were documented in SLE patients with kidney damage, demonstrating a decreased frequency of these cells in patients who responded to therapy." (PMID 35663936, 2022).
Lassa fever (1 paper, 2021). A viral hemorrhagic fever that is caused by the Lassa virus, which is transmitted by contact with infected rodents; it is characterized by fever, headache, malaise, myalgia, and hearing loss. "We assessed CD45RA, CD27, and CD28 levels to investigate the phenotypes of circulating effector/memory T cells induced during Lassa fever." (PMID 33398113, 2021).
lung adenocarcinoma (1 paper, 2022). A carcinoma that arises from the lung and is characterized by the presence of malignant glandular epithelial cells. "However, sPD‐L2 and sPD‐1 were only overexpressed in lung adenocarcinoma patients, and the serum levels of CD27 and CD152 were markedly elevated in patients with lung squamous cell carcinoma, but not lung adenocarcinoma patients." (PMID 35019173, 2022).
lymphoid tumors (1 paper, 2020). "While the BsAb targets CD27 for costimulation of T cells to enhance general antitumor activity, an alternative mechanism involving ADCC enabled by FcR binding may also contribute to antitumor effects in certain lymphoid tumors expressing CD27." (PMID 32451681, 2020).
lysinuric protein intolerance (1 paper, 2021). Lysinuric protein intolerance (LPI) is a very rare inherited multisystem condition caused by disturbance in amino acid metabolism. "HLH has also been associated with other Mendelian disorders affecting inflammation, including lysinuric protein intolerance caused by SLC7A7 defects, and CD27 and ITK deficiency caused by autosomal recessive changes in CD27 and ITK, respectively." (PMID 34677667, 2021).
malignant pleural mesothelioma (1 paper, 2021). A malignant neoplasm that arises from mesothelial cells in the pleura and shows a diffuse growth pattern. "In addition, CD70 expression on malignant pleural mesothelioma and lower CD27–positive TIL accumulation are reported to correlate with poor prognosis." (PMID 35145909, 2021).
MALT lymphoma (1 paper, 2025). An indolent, extranodal type of non-Hodgkin lymphoma composed of small B-lymphocytes (centrocyte-like cells). "Immunofluorescence double staining technique showed the co-expression of CD70 and CD27 in MALT lymphoma samples." (PMID 40078987, 2025).
mastitis (1 paper, 2023). Inflammation of breast tissue during lactation or postpartum due to an obstructed duct or infection. "We found that a considerably decreased proportion of CD27+IgG+ B cells (in total B cells) was observed in the B. contaminans naturally-induced mastitis cows, which was related to B. contaminans infection." (PMID 36960295, 2023). "And on this basis we determined the percentages of CD27+ T cells and CD44+ T cells in the αβ or γδ T cells subsets of the healthy and B. contaminans naturally-induced mastitis cows to assessment the differentiation and activation of T cells." (PMID 36960295, 2023). "Our results, for the first time, revealed a potential role of IgG+CD27+ B cells, CD4+CD8+ T cells and WC1+ γδ T cells in the defense of B. contaminans-induced mastitis in cows." (PMID 36960295, 2023).
measles (1 paper, 2018). A highly contagious viral infection caused by the measles virus. "In the B cell population, there was a significant decrease in the frequency of total circulating B cells, mainly due to the loss of CD27− and CD27+ immunoglobulin class-switched memory B cells after measles." (PMID 30470742, 2018).
mild cognitive impairment (1 paper, 2020). "Furthermore, recently an increase in CD3+CD8+CD45RA+CD27– TEMRA T cells was reported in mild cognitive impairment (MCI) or AD patients." (PMID 32982670, 2020).
monoclonal gammopathy of undetermined significance (1 paper, 2024). "Recent studies have highlighted that during the transition from monoclonal gammopathy of undetermined significance (MGUS) to MM, there’s a discernible decline in MM-derived CD27 antigen levels." (PMID 38504180, 2024).
nephritis (1 paper, 2022). Inflammation of renal tissue. "Extrafollicular active Naive (aNAV) and Double Negative type 2, DN2 (CD27− IgD− CD21− CD11c+) B cells were expanded in severe active patients and were associated with nephritis." (PMID 36148466, 2022).
neutropenia (1 paper, 2013). A decrease in the number of neutrophils found in the blood. "The high frequency of neutropenia and long-term decrease in CD27+ memory B cells in our patients may reflect a biological synergism of the proposed combination of RTX and MTX with MP." (PMID 24109519, 2013).
oral cancer (1 paper, 2021). "This is contradictory with the results in the current computational prediction regarding oral cancer, which may be attributed to CD27 acting as either a costimulatory or coinhibitory receptor in different cancers and different circumstances." (PMID 35127742, 2021). "The low expression of three ICGs positively correlated with CD274 (BTLA, CD27, and CTLA4) indicated a better prognosis compared to their high expression, indicating their coinhibitory roles in the tumor immunology of oral cancer." (PMID 35127742, 2021).
osteoporosis (1 paper, 2024). A condition of reduced bone mass, with decreased cortical thickness and a decrease in the number and size of the trabeculae of cancellous bone (but normal chemical composition), resulting in increased fracture incidence. "The OR of CD24+ CD27+ %B cell (B cell panel) risk on Osteoporosis was estimated to be 0.9991 (95% CI = 0.9984~0.9998, P = 0.021)." (PMID 39086903, 2024). "According to MR results, the traits IgD+ CD24+ %B cells, CD24+ CD27+ %B cells, and CD25 on IgD+ (B cell panel) have been identified as protective factors against osteoporosis." (PMID 39086903, 2024). "CD24, CD27, CD25 from B cells are protective factors against osteoporosis, and similar findings have been discussed, but more in-depth mechanisms of action remain to be investigated." (PMID 39086903, 2024).
Pleural effusion (1 paper, 2017). The presence of an excessive amount of fluid in the pleural cavity. "However, there was an elevated population of memory (CD45RA−CD45RO+CD27+CD28+) CD8+ T cells and a low proportion of terminally differentiated (CD45RA+CD45RO−CD27−CD28−) CD8+ T cells in the pleural effusions." (PMID 28101811, 2017).
polyp (1 paper, 2024). A usually exophytic mass attached to the underlying tissue by a broad base or a thin stalk. "Eubacterium oxidoreducens induced polyp development by mediating the levels of CD45 on CD66b++ myeloid cells and CD20 on IgD- CD27- B cells, which exert a suppressive effect on polyp development." (PMID 39346904, 2024).
preeclampsia (1 paper, 2019). Preeclampsia is a hypertensive disorder of pregnancy that is characterized by new-onset hypertension with proteinuria presenting after 20 weeks of gestation, and depending on mild or severe forms may initially present with severe headache, visual disturbances, and hyperreflexia. "In preeclampsia, CD8+ CM cell proportions and their CD28 and CD27 expression were comparable to the proportions in healthy women, both in peripheral blood and in a swab from the intrauterine cavity." (PMID 31001255, 2019). "In preeclampsia, CD8+ EM cell proportions and their CD27 and CD28 expression were comparable to CD8+ EM cell proportions in healthy women in peripheral blood and in a swab from the intrauterine cavity." (PMID 31001255, 2019).
primary biliary cirrhosis (1 paper, 2016). "In primary biliary cirrhosis, a disease characterized by elevated IgM level, bacterial cytosine-guanine dinucleotides were suggested to enhance IgM production by CD27+ memory B cells." (PMID 27123003, 2016).
progeria (1 paper, 2025). "Many genes, such as CCL2 and UCP2, were upregulated in progeria whilst CD27, CD28, and TIGIT were dysregulated in senescent cells." (PMID 40343591, 2025).
psychosis (1 paper, 2021). "Previous studies have reported that the number of CD4+CD27+CD28+ cells in elderly patients with psychosis is lower than that in young patients." (PMID 34955935, 2021).
rectum adenocarcinoma (1 paper, 2019). An adenocarcinoma arising from the rectum. "High expression of CD28 and CD27 in HPV-positive HNSC and cytomegalovirus-positive colon and rectum adenocarcinoma tumors suggest an increase in the presence of CD28+CD27+ T-cells compared to virus-negative HNSC tumors and virus-negative colon and rectum adenocarcinoma tumors." (PMID 30911684, 2019).
renal carcinoma (1 paper, 2025). A carcinoma arising from the epithelium of the renal parenchyma or the renal pelvis. "We also showed that CD27 expression was enriched in exhausted CD8+T cells, which is consistent with our previous findings in renal cancer." (PMID 40148586, 2025).
Rotavirus infection (1 paper, 2016). Infection with any of the rotaviruses. "Additional studies in mice have pointed to the importance of the α4(high)β7(high)CD27(intermediate) phenotype as well; among memory B cells, only α4β7 (but not α4+β7(negative)) cells gave protection against rotavirus infection in a mouse model." (PMID 27881837, 2016).
rubella (1 paper, 2023). A viral infection caused by the rubella virus. "That the levels of T cells and activated T cells (CD27+ and CD25+CD127+) can negatively influence the level of the emerging IgA response to rubella is also not surprising, as is the negative impact of IL-10, IFN-γ and the level of initially activated helpers (CD3+CD8−CD38+)." (PMID 36851738, 2023).
serous carcinomas (1 paper, 2022). "Of the proteins assayed, only CD27 and CD28 showed statistically significant differences in median serum levels in patients with serous vs. non-serous carcinomas (p = 0.03, p = 0.04, respectively)." (PMID 35204342, 2022).
serous ovarian cancer (1 paper, 2024). "This study aimed to develop and evaluate radiomics models to predict CD27 expression and clinical prognosis before surgery in patients with serous ovarian cancer (SOC)." (PMID 38909269, 2024).
severe congenital neutropenia (1 paper, 2019). "In patients with severe congenital neutropenia (SCN), CD27+IgDlow circulating MZ B cells and levels of IgM, IgG, and IgA antibodies against T cell-independent antigens were less abundant than in healthy subjects." (PMID 31507592, 2019).
skin infection (1 paper, 2018). An inflammatory process affecting the skin, caused by bacteria, viruses, parasites, or fungi. "The frequency of skin infections correlated with the proportion of CD62L+ T cells, naïve CD4+ and CD27+ CD8+ T cells and with activated B cells." (PMID 30477583, 2018). "The skin infection frequency and need for antibiotic usage correlated with the proportion of CD62L+ T cells, naïve CD4+ and CD27+ (intermediate memory) CD8 cells and with activated B cells." (PMID 30477583, 2018).
T-cell deficiency (1 paper, 2024). "Other diagnostic clues include a decrease in switched memory B cells (CD19+ IgM-/D- CD27+) below 70% of normal values for age or the absence of significant T-cell deficiency." (PMID 38953064, 2024).
T-cell immunodeficiency (1 paper, 2023). A broad classification of disorders that affect the cell-mediated aspect of the immune response. "Continuous stimulation of CD27 by constitutive expression of CD70 on B cells resulted in increased apoptosis and depletion in NK cells or T-cell immunodeficiency." (PMID 37180119, 2023).
type 2 diabetic (1 paper, 2020). "A significant increase in T cell immunosenescence, as based on multiple markers (including naïve cell markers CD27/CD45RO, CD28, CD127 and CD57), is observed in type 2 diabetic patients with eGFR below 60 ml/min." (PMID 33088331, 2020).
typhoid fever (1 paper, 2016). A bacterial infectious disorder contracted by consumption of food or drink contaminated with Salmonella typhi. "However, following wild-type challenge, Sm CD27+ and Um cells showed a significant reduction in their frequency AroundTD in TD volunteers (compared to NoTD), which suggest that some B cell subsets are more affected than other by typhoid fever." (PMID 27300136, 2016).
vitiligo (1 paper, 2022). Generalized well circumscribed patches of leukoderma that are generally distributed over symmetric body locations and is due to autoimmune destruction of melanocytes. "Regarding CD27, its soluble serum level was elevated in patients with active vitiligo and was suggested as a marker of disease progression." (PMID 35300124, 2022).
tumor (454 papers, 2003 to 2026). "Naïve B cells and CD27+ unswitched memory B cells are linked to indolent tumor behavior and favorable prognosis, highlighting their potential as biomarkers for risk stratification and non-invasive monitoring in PTC management." (PMID 41929497, 2026). "Advanced microscopy techniques indicated that CD27- γδ T cells are enriched in tumors, whereas CD27+ γδ T cells are more prone to interact with macrophages in tumor-associated adventitial cuffs." (PMID 41779856, 2026). "CD70 is markedly expressed in hematological malignancies, activating signaling pathways via its interaction with CD27, which mediates T cell exhaustion, enhances Treg function, and recruits tumor-associated macrophages." (PMID 41155287, 2025). "Engineered anti-CD27 antibodies capable of tetravalent binding to CD27 and selective FcγRIIB association exhibit potent T cell stimulatory activity and anti-tumor efficacy in pre-clinical models, compared to bivalent counterparts." (PMID 41422231, 2025). "CD27, whose expression in MM varies, has been linked to patient outcomes; specifically, diminished CD27 expression correlates with a heightened tumor burden and suboptimal therapeutic responses." (PMID 38504180, 2024). "Previous studies have highlighted that the co-stimulatory molecule CD27 is associated with T cell activation and is up-regulated in tumor-specific CD4 + T cells." (PMID 39033098, 2024). "In this respect, the development of Tregs and increased Tregs activity in the TME are linked to CD27 agonism by CD70+ tumor cells." (PMID 37545491, 2023). "Binding of a bsAb to a tumor-associated antigen can serve as a cross-linking platform for CD27 on T cells." (PMID 37545491, 2023). "In tumor-associated lungs, the systemic increase in IL-1β and IL-23 induces CD27− γδ T cells to expand and rapidly produce cytokines." (PMID 36480166, 2023). "CD27+CD21+ B cells are potential therapeutic targets in NSCLC immunotherapy because of their association with tumor progression and enhanced expression of the Tregs effector T-cell response." (PMID 37828063, 2023). "CD70 is also implicated in tumor cell and regulatory T cell survival through interaction with its ligand, CD27." (PMID 36588677, 2022). "Extensive studies have been conducted to investigate the underlying mechanism by which CD40LG and CD27 modulate tumor immunity." (PMID 36061181, 2022). "Tumor growth was clearly reduced and survival of the mice was prolonged compared to untreated controls suggesting a synergistic effect of CD27 deficiency in the Treg compartment and blockade of the PD-1 signaling pathway on antitumor immunity." (PMID 34423375, 2022). "We found that the proliferation of CD27− γδ T cells was inhibited when cultured with tumor-associated neutrophils, but not with bone marrow–derived neutrophils from either tumor-bearing or tumor-free mice." (PMID 29750788, 2018). "Our previous work demonstrated that a soluble factor from tumor cells is able to induce a suppressor phenotype (SP) in human CD8+ T cells typified by loss of CD27/CD28 expression and acquisition of a potent suppressor function." (PMID 28806909, 2017). "This suggests that, while T cells are important, additional mechanisms of tumor killing compensate for the loss of T cell cytotoxicity in the anti-CD20/CD27-treated cohorts." (PMID 29198913, 2017). "The anti-tumor activity of these anti-CD27 mAbs was shown to require IFN-γ and is associated with an increase in effector cells in the tumor." (PMID 26500773, 2015). "The expanded clones had an effector memory phenotype with high cell surface expression of CD27, an attribute that was associated with tumor regression with TIL therapy." (PMID 18937837, 2008). "Further, the number of CD27+/CD8+ T cells in bulk TIL was associated with the ability of these TIL to mediate tumor regression following adoptive transfer." (PMID 18937837, 2008).